IL6 (interleukin 6)
Diseases named in the same sentence as IL6 in open-access papers (continued):
Sharing a sentence is not in itself a finding about the gene and the disease.
lung carcinoma (continued). "CAFs isolated from lung cancer tissue promote metastasis by secreting IL-6, which activates JAK2 and STAT3 signaling and also induces EMT via increasing vimentin expression in lung cancer cells both in vitro and in vivo." (PMID 36620544, 2022). "Across the three groups, serum levels of CEA, IL-1β, IL-6, and IL-8 were highest in the lung cancer group, and the differences among the three groups were statistically significant (p = 0.000)." (PMID 35928100, 2022). "We found that CCL3, CCL4, and CSF1 were significantly upregulated in IL17D–expressing human lung cancer cells, whereas Ccl3, Ccl4, and Il6 were induced in IL17D–expressing murine lung cancer cells." (PMID 35939336, 2022). "Inflammatory cytokines related to lung cancer include IL-1β, IL-4, IL-6, IL-11, IL-12, TNF-α, monocyte chemotactic protein (MCP)-1, and TGF-β." (PMID 35898583, 2022). "In a marker phase I trial, ApoC1 in tumor tissue is highly expressed in late-stage lung cancer and the over-expression is positively correlated with interleukin-6 (IL-6), a molecule that can foster lung cancer cell proliferation." (PMID 36506554, 2022). "Neutrophil depletion, as well as IL-6 blockade, were associated with enhanced anti-PD1 immunotherapy efficacy in 2 lung cancer murine models." (PMID 36010840, 2022). "In lung cancer, mesenchymal stem cells can enhance tumorigenesis by activating IL-6/JAK2/STAT3 pathway." (PMID 36591515, 2022). "Meanwhile, increased levels of interferon-γ, interleukin (IL)-6, and 8 were examined in the serum of lung cancer patients." (PMID 35371315, 2022). "By contrast, an NF-κB inhibitor decreased IL-6 mRNA levels in TKI-resistant lung cancer up until 24 h, which then increased again by 48 h." (PMID 35740609, 2022). "High expression of certain cytokines (including IL-6, IL-8, and TNF-α) was linked to cancer cachexia, as exemplified by that IL-6 enclosed in lung cancer-derived extracellular vesicles would evoke muscle wasting by activating STAT3 pathway." (PMID 36581870, 2022). "Clazakizumab, an anti‐IL‐6 antibody, was tested in patients with non‐small cell lung cancer and improved cachexia and anaemia in phase I and II trials." (PMID 35080147, 2022). "In agreement with our data, elevated levels of IL-1 and IL-6 were found in patients after radiation therapy for lung cancer." (PMID 34277544, 2021). "The combination of IL-6 blocking and other signal pathway inhibition has been widely studied in lung cancer." (PMID 34079469, 2021). "A study has confirmed that IL-6 expression contributed to the survival of head and neck cancer, and IL-6 expression also played a significant role in the survival of lung cancer." (PMID 34165442, 2021). "Previous studies indicated that MALT1 was required for the EGFR- and TNF-α/NF-κB signaling-induced IL-6 production in lung cancer progression." (PMID 33802402, 2021). "We found that the BLT2 cascade lies downstream of mutant KRAS and contributes to mutant KRAS-driven lung cancer cell proliferation and IL-6 production." (PMID 34635780, 2021). "In lung cancer cells, PD-L1 levels can be altered by radiation via the IL-6-MEK/ERK signaling pathway, which can help cancer cells escape killing by natural killer (NK) cells." (PMID 34805266, 2021). "The expression level of IL-6 was measured by IL-6 sandwich ELISA after treating human lung carcinoma cell line A549 with IL-1β and Canakinumab, pro-Canakinumab, MMP-9 pre-incubated Canakinumab or MMP-9 pre-incubated pro-Canakinumab, respectively." (PMID 34290297, 2021). "For example, the presence of CAFs is correlated with a poor prognosis, and CAF-secreted cytokines (IL-6 and IL-8) confer drug resistance in lung cancer." (PMID 34646392, 2021). "Our findings suggest a working model in which MEK inhibition in lung cancer cells induces secretion of the Th17 differentiating cytokines IL-6, TGF-β, and IL-23." (PMID 33972557, 2021). "Increased IL-6 serum levels have been demonstrated in several cancers including breast and lung cancer." (PMID 34671021, 2021).
lung carcinoma (continued). "Siltuximab, as an anti-IL-6 monoclonal antibody, was found to have strong tumor suppressive effects in lung cancer xenograft models treated with CAFs." (PMID 35087824, 2021). "miR-218 was recently reported to play a tumor suppressive role in lung cancer through regulation of the IL6/STAT3 pathway." (PMID 33859751, 2021). "High IL6 expression can eliminate the anti-tumor effect of the inhibitor RO4929097 in lung cancer and glioma." (PMID 33644115, 2021). "The concentrations of IL-6 between lung cancer stages were the only statistically significant difference in the analysis of variances (p = 0.0175)." (PMID 34439874, 2021). "Treatment with BLT2 cascade inhibitors clearly suppressed IL-6 production and lung tumor nodule formation in a KrasG12D-driven lung cancer mouse model." (PMID 34635780, 2021). "In the subgroup of lung cancer patients, IL-6 level at FU1 and FU2 correlated with OS (FU1: HR: 1.127, 95% CI: 1.036–1.226, p = 0.006, FU2: HR: 1.094, 95% CI: 1.011–1.184, p = 0.027)." (PMID 34830880, 2021). "In A549, a lung cancer cell line, IL-6 is known to use phosphatidylinositol-4,5-Bisphosphate3-Kinase/Threonine Kinase-1/AKT Serine (PI3K/AKT) signal to trigger its growth." (PMID 34336101, 2021). "Combined detection of PCT and IL-6 can be an effective means to identify complications after lung cancer surgery." (PMID 34690780, 2021). "To further confirm the correlation between IL1A, IL6, and HIF1α, we analyzed the expression of these two genes in 16 patients with lung cancer." (PMID 34362882, 2021). "Increase in IL-6, IL-10, NLR, PLR, and LDH levels or reduced ALC and ALB levels were associated with the occurrence of CIP in lung cancer patients." (PMID 34327140, 2021). "Interleukin-6 (IL-6) also exerts a significant function in lung cancer by inducing a COPD-like inflammatory response." (PMID 34512172, 2021). "Circulating IL-6 levels showed positive correlation to both survival and lean body mass in patients with advanced lung cancer." (PMID 33925872, 2021). "Murine models of lung carcinoma harbouring oncogenic KRAS mutations exhibited enhanced proliferation and immunosuppressive IL-6 production by myeloid cells within the TME." (PMID 34944851, 2021). "STAT3 pathway was reported to be the most critical downstream of IL-6 signaling that modulated PD-L1 in lung cancer cells." (PMID 34429133, 2021). "Studies have found that the serum levels of PCT and IL-6 after lung cancer surgery are higher than those before surgery." (PMID 34690780, 2021). "Results of our current comprehensive study of cytokines did reveal that the transfection of miR‐1 into three different human lung carcinoma cell lines harboring EGFR mutations significantly decreased the expression of CCL5, CXCL10, IL‐6, IL‐8, and TNF‐α." (PMID 33305905, 2021). "The pro-inflammatory cytokines, GRO, MCP-1, IL-8, and IL-6, purportedly promote lung cancer development and progression." (PMID 33562773, 2021). "IL-6 contributes to lung cancer progression by triggering pro-inflammatory pathways that enhance cancer cell proliferation; thus, IL-6 is considered a marker of poor prognosis in lung cancer." (PMID 34635780, 2021). "In lung cancer cells, Nodal can promote the malignancy of cancer cells via activation of NF-κB/IL-6 signal pathways." (PMID 33754002, 2021). "CCL2 (or monocyte chemotactic protein 1 (MCP1)) displays overexpression in TAM and triggers EMT in lung cancer with IL-6 through activation of Twist/STAT3." (PMID 34220337, 2021). "In conclusion, we found that Rab37-mediated exocytosis of IL-6 from macrophages promotes PD-1 upregulation in T cells via the Rab37/IL-6/STAT3 transcription axis to support lung cancer progression." (PMID 34093869, 2021). "Studies on lung cancer patients have shown a relationship between IL-6 and cancer cachexia and cancer-related fatigue." (PMID 33925400, 2021).
lung carcinoma (continued). "The inflammatory factors closely related to lung cancer are IL-1β, IL-4, IL-6, IL-11, IL-12, TNF-α, MCP-1, and transforming growth factor (TGF)-β." (PMID 34079469, 2021). "Statins inhibit the survival of lung cancer cells by inhibiting the secretion of CCL3 by lung cancer cells as well as IL-6 and CCL2 secretion by mesenchymal stromal cells, indicating the potential of statins as repurposed drugs for targeting the immune TME." (PMID 34303383, 2021). "IL-6 plays an important role in early stages of lung cancer and potentiates immune responses resulting in cell proliferation and expansion of the tumor mass." (PMID 34790566, 2021). "In the present study, we identified ERK5 as an important regulator of IL-6 in several lung cancer cell lines." (PMID 34671021, 2021). "Prior studies have reported that serum cytokine levels correlated with survival in lung cancer patients; in particular, IL-6, IL-8 and TNF-α." (PMID 34830880, 2021). "Further, Wang and colleagues depicted that IL6 pretreatment of CD133+/CD44+ cells assisted in entering into the cell cycle in quiescent lung cancer stem cells and significantly increased chemosensitivity." (PMID 33925297, 2021). "The concentration of circulating SCFAs in the intestine affects IL-6 and IL-8 in lung cancer and is related to the occurrence and development of lung cancer." (PMID 33494784, 2021). "Elevated IL-6 levels above the reference threshold and a correlation between this cytokine and the metastatic biomarker MMP-9 indicate a higher risk of lung cancer aggressiveness." (PMID 34439874, 2021). "(2010) on lung cancer cells show that factors like IL-6 and TGF-β can act in unison prominently contributing toward resistance to chemotherapy." (PMID 35127527, 2021). "Biochanin A, an O-methylated isoflavone, inhibited the release of pro-inflammatory cytokines TNF-α and IL-6 from A427 lung cancer cells using the cocultured method." (PMID 34950252, 2021). "Multiplex fluorescence immunohistochemistry was performed to detect the protein level of Rab37, IL-6 and PD-1 and localization of the tumor-infiltrating immune cells in allografts from mice or tumor specimens from lung cancer patients." (PMID 34093869, 2021). "Unfortunately, IL-6 blockade has limited effectiveness in lung cancer patients, and therefore, alternative molecular targets are required." (PMID 34635780, 2021). "In our study, patients with lung cancer showed a drop in IL-6 levels during and at the end of treatment, while patients with esophageal cancer showed a decrease in IL-6 levels during treatment but an increase at the end of treatment." (PMID 34830880, 2021). "Studies have shown that, in lung cancer, Interleukin 6 (IL‐6) can not only promote the self‐renewal of CD133+ CSC‐like cells but also promote DNA repair and protect CD133+ CSC‐like cells from apoptosis and death." (PMID 34766149, 2021). "In patients with advanced lung cancer, IL-6 and LDH had considerably higher concentration and activity." (PMID 34439874, 2021). "At different stages of lung cancer, IL-6's mechanisms upregulated CCL-2/5 and played a part in the EMT and therapy resistance, a recent study in in vivo mouse and in vitro human lung tumour representations indicated." (PMID 34336101, 2021). "The mono-cultured human THP-1 macrophages, human Jurkat T cells and A549 lung cancer cells or co-cultured A549 with Jurkat T cells secreted a little IL-6 into the CM (Bars 1-4)." (PMID 34093869, 2021). "In lung cancer patients, metformin has also been shown to reduce IL-6 driven epithelial-mesenchymal transitions, which plays an important role in tumorigenesis." (PMID 34829914, 2021). "High IL-6 activity is correlated with poor prognosis and lung-cancer-related symptoms such as fatigue, thromboembolism, cachexia, and anaemia." (PMID 34834295, 2021). "Elevated IL‐6 levels are observed in patients with different types of cancer, such as breast, cervical, colorectal, and nonsmall-cell lung cancer (NSCLC)." (PMID 34131122, 2021).
lung carcinoma (continued). "In this study, we revealed that ectopic expression of miR-19a or miR-19b-1 modulated the expression of IL-related genes (including IL1B, IL11RA, IL20RB, IL6 and IL32) and suppressed IL6 production in lung cancer and NPC cells." (PMID 32308549, 2020). "For instance, in lung cancer, IL-6 regulates the expression of MMP-3 through ATM phosphorylation, a potential factor associated with drug resistance in this cancer type." (PMID 33392094, 2020). "Activated astrocytes produce IL-6, which in turn promotes lung cancer cell proliferation in Seike’s study." (PMID 33537237, 2020). "As MK2 was shown to be involved in NF-κB-dependent transcription, we performed experiments to investigate the role of MK2 in TNF-α stimulated IL-6 transcription in lung cancer cells." (PMID 32647362, 2020). "Sun and colleagues have also discovered that 2- hydroxy-3-methylanthraquinone can inhibit lung cancer cell growth and invasion by downregulating IL-6-induced JAK2/STAT3 pathways." (PMID 33299414, 2020). "The kidneys of the lung cancer mice expressed relatively more IL-6, particularly those of the mice transplanted with 5 × 106 LLC1 cells." (PMID 33260558, 2020). "We observed that collected media from Ab-treated cells were able to revert TAM phenotype induced by lung cancer spheroids as indicated by a decrease of IL-10 and an increase of IL-6 and IL-12 (the latter was observed only after moAb treatment)." (PMID 33123122, 2020). "It is reported that the simultaneous increase in the expression of IL-6 and tumor markers contributed to the worse prognosis of lung cancer patients." (PMID 32595734, 2020). "Among them, TNF had the greatest degree in the HCT-major hub genes-disease network, while IL-6, JUN, EGFR, and MYC were shown to associate with the survival of lung cancer patients." (PMID 32595734, 2020). "In this study, A549 lung carcinoma cells exposed to PM10 showed increases of IL-6 and phosphorylation of JAK1/JAK2/STAT3 signaling molecules." (PMID 33374928, 2020). "Metformin overcomes IL-6-induced EGFR-TKI resistance in TKI-sensitive lung cancer cells through the inhibition of STAT3 and AKT phosphorylation and the enhancement of AMPK activation." (PMID 32041944, 2020). "Our finding here highlights the potential role of TIM‐4 in enhancing metastasis of NSCLC and provides a new mechanism in IL‐6 promoting lung cancer progression." (PMID 32020709, 2020). "IL-6 and STAT3 are implicated in the malignancy of lung cancers, and many studies have attempted to target IL-6/IL-6 receptor for drug development." (PMID 31900385, 2020). "In summary, the data presented in this study suggest that IL‐6 in tumour microenvironment enhance TIM‐4 expression in lung cancer cells, which in turn promotes metastasis and IL‐6 production of lung cancer cells." (PMID 32020709, 2020). "Subsequently, we further confirmed that IL‐6 promoted migration of lung cancer cells, decreased E‐Cad and increased N‐Cad, which was consistent with IL‐6 promoting tumour metastasis." (PMID 32020709, 2020). "The abnormally increased secretion of IL-6 was related to the regulation of growth and metastasis of lung cancer cells, and the activation of the IL-6/AK2/STAT3 pathway enhanced initiation of tumor in lung cancer." (PMID 32595734, 2020). "TLR4-induced autophagy activation promoted migration and invasion of lung cancer by induction of chemokines and immunosuppressive factors, such as IL-6, MMP2, and CCL2." (PMID 33172060, 2020). "Research has uncovered a role for CCL5 in KRAS-induced lung cancer, where it is involved in a cytokine circuit along with IL-6 and STAT3 driving tumorigenesis." (PMID 33116132, 2020). "Both NF‐κB and STAT3 pathways regulate IL‐6 production, which plays an important role in the development and prognosis of lung cancer." (PMID 32020709, 2020).
lung carcinoma (continued). "PLD is involved in the induction of the preresorptive cytokine, IL-6, in osteoblasts and is required for lung cancer-derived IL-8-induced osteoclastogenesis and IL-15-mediated osteoclastogenesis in RASF." (PMID 32370217, 2020). "Above all, the results showed that TIM‐4 expression in lung cancer cell lines was up‐regulated after IL‐6 stimulation." (PMID 32020709, 2020). "Investigating renal inflammation in the lung cancer mice, the distributions of IL-6 and MCP-1 in the kidneys were evaluated by immunohistochemical staining." (PMID 33260558, 2020). "Knocking down FAS promoted lung cancer cells growth through NFkB activation-mediated enhanced IL6 secretion and subsequent STAT3 activation." (PMID 32963220, 2020). "In this study, we demonstrated that DDIAS promoted IL-6–mediated STAT3 activation in lung cancer cells by competing with PTPRM." (PMID 31900385, 2020). "In this study, serum BME cytokines (CaN, OPG, PTHrP, and IL-6) and bone turnover markers (tP1NP and β-CTx) were measured in lung cancer patients." (PMID 32546271, 2020). "The stimulation of cancer cells with IL-6 was shown to abrogate sensitivity to cisplatin and increased the formation of tumour spheres induced by high-fat diets in in vivo mouse models of lung cancer." (PMID 32731620, 2020). "High interleukin-6 (IL-6) expression is common in patients with lung cancer and is indicative of poor prognosis." (PMID 31900385, 2020). "In line with the role of IL6 in lung tumor, the signal transducers and activators of transcription 3 (STAT3), the well defined downstream effector of IL-6, also prevents lung cancer initiation." (PMID 32134471, 2020). "First, it has been found that the expression of colony stimulus factor 1 (CSF-1) and interleukin-6 (IL-6) in non-small cell lung cancer (NSCLC) is closely associated with the infiltration of TAMs in tumor stroma and the progression of lung cancer." (PMID 33224886, 2020). "In contrast, OSM and IL-6 are expressed in breast, prostate, and lung cancer cell lines, and promote tumor development by modulating lipid metabolism, matrix degradation, angiogenesis, and cellular dedifferentiation." (PMID 33216732, 2020). "Impact of PSD-A over TPA and IL-6 induced STAT3 activation has been disclosed previously in lung cancer." (PMID 33013353, 2020). "In lung cancer, IL-6/STAT3 signalling induced by KRAS oncogene has contrasting roles in its initiation and progression." (PMID 33116132, 2020). "On the other hand, IL-6, produced by cancer-associated fibroblasts (CAFs), induces invasion, metastasis, and EMT properties in lung cancer via STAT3 pathway." (PMID 33352869, 2020). "In this study, UPS4 knockdown in multiple lung cancer cell lines increased the production of IL-6 as well as stemness properties." (PMID 31936290, 2020). "A similar circadian organising effect of disease was reported for lung cancer, mediated by IL-6, or in response to changes in the gut microbiome, mediated by polyamine metabolites." (PMID 30728072, 2019). "In fact, IL-6/STAT3 signaling has been shown to suppress lung cancer initiation while promoting cancerous cell proliferation, migration, and disease progression by positively modulating the induction of cyclin D1." (PMID 31547048, 2019). "The significantly suppressive effect of miR‐206 on IL6‐induced gefitinib‐resistant EGFR‐mutant lung cancer cells prompted us to investigate its downstream signalling pathway." (PMID 31507089, 2019). "In lung cancer mouse models, blocking or deleting IL-6 reveals a delay in tumor progression and metastasis through deactivation of the IL-6/STAT3 pathway and cell proliferation regulator cyclin D1, as well as through enhancement of tumor cell apoptosis." (PMID 32039025, 2019). "Pearson correlation analysis showed that ΔNp63α was positively correlated with IL-6 levels in lung cancer tissues." (PMID 31367260, 2019).